C9orf72 (C9orf72-SMCR8 complex subunit)
Diseases named in the same sentence as C9orf72 in open-access papers (continued):
Sharing a sentence is not in itself a finding about the gene and the disease.
frontotemporal dementia (continued). "Facial Emotion Recognition (FER) and Faux Pas (FP) recognition tests were used to study social cognition within the Genetic Frontotemporal Dementia Initiative (GENFI), a large familial FTD cohort of C9orf72, GRN, and MAPT mutation carriers." (PMID 33221702, 2020). "Many ALS-associated variants, particularly for C9orf72, also contribute to other conditions such as frontotemporal dementia (FTD) and cerebellar disease, suggesting that ALS is a multi-system syndrome." (PMID 33256133, 2020). "Patients with familial amyotrophic lateral sclerosis (ALS) and frontotemporal dementia (FTD) commonly have hexanucleotide repeat (GGGGCC) in the C9orf72 gene causing a decreased c9orf72 expression in the brain and peripheral blood cells." (PMID 33643304, 2020). "A hexanucleotide repeat expansion (GGGGCC) in the first intron of the C9orf72 gene has been linked to the pathogenic mechanism of two diseases: familial amyotrophic lateral sclerosis (fALS) and frontotemporal dementia (FTD)." (PMID 31141951, 2019). "The C9orf72 genetic mutation is the most common cause of familial frontotemporal dementia (FTD) and motor neuron disease (MND)." (PMID 30233460, 2018). "C9orf72 is associated with frontotemporal dementia (FTD) and Amyotrophic Lateral Sclerosis (ALS), both of which are devastating neurodegenerative diseases." (PMID 29479499, 2018). "About 10 % of all patients with amyotrophic lateral sclerosis (ALS), frontotemporal dementia (FTD) or mixed presentation of both diseases (ALS/FTD) are caused by a massive expansion of a GGGGCC repeat upstream of the C9orf72-coding region." (PMID 26085200, 2015). "Most recently, the GGGGCC repeat expansion in the C9orf72 gene has been shown to be associated with amyotrophic lateral sclerosis/frontotemporal dementia (ALS/FTD)." (PMID 26650351, 2015). "Recently, the leading genetic cause of amyotrophic lateral sclerosis (ALS) and frontotemporal dementia (FTD) has been linked to an expanded (GGGGCC)·(GGCCCC) repeat in the C9orf72 gene which also shows length variation between tissues of a given individual." (PMID 25147206, 2014). "An expanded hexanucleotide GGGGCC repeat located in the first intron of the C9orf72 gene represents the most common genetic cause of familial frontotemporal dementia (FTD) and amyotrophic lateral sclerosis (ALS)." (PMID 22898310, 2012). "Frontotemporal dementia (FTD) is a common cause of early-onset dementia with a significant genetic component, as underlined by the recent identification of repeat expansions in the gene C9ORF72 as a major cause of FTD and motor neuron disease." (PMID 23006986, 2012). "Intronic hexanucleotide repeat expansions in the C9orf72 gene represent the most common genetic cause of the neurodegenerative diseases amyotrophic lateral sclerosis (ALS) and frontotemporal dementia." (PMID 41961863, 2026). "The C9orf72 hexanucleotide repeat expansion mutation is the most common genetic cause of amyotrophic lateral sclerosis (ALS) and frontotemporal dementia, but its cell type‐specific effects on energy metabolism and immune pathways remain poorly understood." (PMID 40888599, 2026). "A GGGGCC repeat expansion in C9orf72 is the most common genetic cause of amyotrophic lateral sclerosis (ALS) and frontotemporal dementia (FTD)." (PMID 41884597, 2026). "The study focused on repeat expansions of G4C2 (r(G4C2)exp) in chromosome 9 open reading frame 72 (C9orf72) gene, which are causative of amyotrophic lateral sclerosis (ALS) and frontotemporal dementia (FTD)." (PMID 41226803, 2025). "Amyotrophic lateral sclerosis (ALS) and frontotemporal dementia (FTD) are neurodegenerative disorders characterized by the expansion of GGGGCC (G4C2) repeats in the C9orf72 gene and progressive motor neuron degeneration." (PMID 41005474, 2025). "More ASOs, including BIIB078 and Wave Life Sciences’ WVE-004, specifically target C9orf72 repeat expansions, an area believed to be the most common genetic cause of ALS and frontotemporal dementia." (PMID 41272780, 2025).
frontotemporal dementia (continued). "The abnormal expansion of GGGGCC (G4C2) repeats in the noncoding region of the C9orf72 gene is a major genetic cause of two devastating neurodegenerative disorders, amyotrophic lateral sclerosis (ALS) and frontotemporal dementia (FTD)." (PMID 40930530, 2025). "The study selection and characteristics are detailed in our accompanying systematic review: C9orf72-related amyotrophic lateral sclerosis-frontotemporal dementia and links to the DDR." (PMID 41245603, 2025). "The most common genetic cause of both familial amyotrophic lateral sclerosis (ALS) and frontotemporal dementia (FTD) is an expanded G4C2 repeat in the first intron of the gene C9orf72." (PMID 41278665, 2025). "Thalamic atrophy is a common finding, especially in ALS patients with frontotemporal dementia (ALS-FTD), primary lateral sclerosis (PLS), or C9orf72 mutation." (PMID 40722307, 2025). "Specifically, we emphasize the G4s formed by the (GGGGCC)n sequence of the C9orf72 gene, which represents the most common genetic cause of amyotrophic lateral sclerosis (ALS) and frontotemporal dementia (FTD)." (PMID 40004056, 2025). "The RNA exosome complex can degrade expanded hexanucleotide repeat RNA in C9orf72 frontotemporal lobar degeneration (FTLD)/amyotrophic lateral sclerosis (ALS) patients." (PMID 40651665, 2025). "Mutations in the chromosome 9 open reading frame 72 (C9ORF72) gene are among the most common genetic causes of inherited ALS (40%) and frontotemporal dementia (FTD) (25%)." (PMID 41294820, 2025). "In frontotemporal lobar degeneration (FTLD), aberrant methylation has been reported in causal disease genes including GRN and C9orf72; however, the genome-wide contribution of epigenetic changes to the development of FTLD remains largely unexplored." (PMID 40619440, 2025). "Pathologically, patients with pathogenic C9orf72 repeat expansions have cytoplasmic accumulation of TAR DNA-binding protein 43 (TDP-43), representing frontotemporal lobar degeneration (FTLD-TDP pathology)." (PMID 40138021, 2025). "The hexanucleotide repeat expansion in the C9orf72 gene accounts for ∼10% of all amyotrophic lateral sclerosis and 10%–15% of all frontotemporal dementia diagnoses, with the two clinical syndromes co-manifesting in a significant number of patients." (PMID 40794569, 2025). "Nucleolar stress has been implicated in the pathogenesis of amyotrophic lateral sclerosis (ALS) and frontotemporal lobar degeneration (FTD), particularly in cases associated with GGGGCC hexanucleotide repeat expansions in the C9ORF72 gene." (PMID 41415602, 2025). "The C9orf72 hexanucleotide repeat expansion is the most common genetic cause of both ALS and frontotemporal dementia (FTD), establishing a significant overlap between these neurodegenerative disorders." (PMID 40563773, 2025). "C9orf72-related amyotrophic lateral sclerosis (ALS)/frontotemporal dementia (FTD) has proven difficult to model in mice." (PMID 39945358, 2025). "The C9orf72 hexanucleotide repeat expansion (HRE) is a common genetic cause of amyotrophic lateral sclerosis (ALS) and frontotemporal dementia (FTD)." (PMID 38242117, 2024). "The abnormal expansion of GGGGCC/GGCCCC hexanucleotide repeats (HR) in C9orf72 is associated with amyotrophic lateral sclerosis (ALS) and frontotemporal dementia (FTD)." (PMID 38738637, 2024). "Subsequently, we analyzed PRDM16-DT expression in postmortem brain tissues (frontal lobe) obtained from patients with frontotemporal dementia (FTD) carrying mutations in C9ORF72, GRN, or MAPT genes, as well as from control individuals that are available via the RiMOD database." (PMID 39207536, 2024). "Hexanucleotide repeat expansions (HREs) in the chromosome 9 open reading frame 72 (C9orf72) gene are the most frequent genetic cause of amyotrophic lateral sclerosis (ALS) and frontotemporal dementia (FTD)." (PMID 38722513, 2024).
frontotemporal dementia (continued). "This phenomenon has been reported in C9orf72-related ALS and frontotemporal dementia, where the C9orf72 GGGGCC repeat is translated into aggregating dipeptide-repeat proteins." (PMID 39456257, 2024). "A non-coding hexanucleotide repeat expansion in the gene C9orf72 is the most common cause of both amyotrophic lateral sclerosis (ALS) and frontotemporal lobar degeneration (FTLD)." (PMID 38641715, 2024). "These are detrimentally affected in different neurodegenerative diseases including amyotrophic lateral sclerosis (ALS) and frontotemporal dementia (FTD), where mutations within the C9orf72 gene represent the most frequent genetic cause." (PMID 39120329, 2024). "Mitochondrial dysfunction is a common feature of C9orf72 amyotrophic lateral sclerosis/frontotemporal dementia (ALS/FTD); however, it remains unclear whether this is a cause or consequence of the pathogenic process." (PMID 38906677, 2024). "Proteinaceous inclusions formed by C9orf72-derived dipeptide-repeat (DPR) proteins are a histopathological hallmark in ∼50% of familial amyotrophic lateral sclerosis/frontotemporal dementia (ALS/FTD) cases." (PMID 39391721, 2024). "A hexanucleotide repeat expansion (HRE) intronic to chromosome 9 open reading frame 72 (C9orf72) is recognized as the most common genetic cause of amyotrophic lateral sclerosis (ALS), frontotemporal dementia (FTD), and ALS-FTD." (PMID 38469573, 2024). "It seems that the (GGGGCC)n hexanucleotide repeat expansion in the C9orf72 gene, plus the intermediate-length CAG expansion in the ATXN2 gene, potentiate the development of an ALS variant characterized by frontotemporal-dementia." (PMID 38877004, 2024). "A hexanucleotide repeat expansion (HRE) in C9orf72 is the most common genetic cause of amyotrophic lateral sclerosis (ALS) and frontotemporal dementia (FTD)." (PMID 38585915, 2024). "Similar pathogenic mechanisms have been proposed for other repeat expansion disorders, such as Fuchs’ endothelial corneal dystrophy, Huntington’s disease [73‒75], and C9orf72-mediated amyotrophic lateral sclerosis/frontotemporal dementia (C9-ALS/FTD) [76‒78]." (PMID 39034824, 2024). "Patients with a C9orf72 hexanucleotide repeat expansion frequently exhibit symptoms from the frontotemporal dementia spectrum and are characterized by earlier age of onset and shorter survival and thus a more aggressive form of ALS." (PMID 38474416, 2024). "Aggregating poly(glycine-alanine) (poly-GA) is derivedfrom theunconventional translation of the pathogenic intronic hexanucleotiderepeat expansion in the C9orf72 gene, which is themost common genetic cause of frontotemporal dementia (FTD) and amyotrophiclateral sclerosis (ALS)." (PMID 38751620, 2024). "The expansion of GGGGCC repeats in the non-coding region of C9orf72 is the most common cause of sporadic and familial forms of ALS and frontotemporal dementia." (PMID 39080077, 2024). "Frontotemporal dementia (FTD) fulfilling the Strong criteria was diagnosed in seven patients (10.94%).C9orf72 repeat expansion was detected in only one case using RP-PCR; the patient had a family history of dementia." (PMID 38464738, 2023). "A recent work demonstrated successful in vivo excision of hexanucleotide repeat expansion in C9ORF72 gene, the most frequent genetic cause of ALS and frontotemporal dementia, by CRISPR/Cas9 machinery." (PMID 37545694, 2023). "The expansion of the G4C2 hexanucleotide repeat in the c9orf72 gene has been identified as the primary genetic cause of familial amyotrophic lateral sclerosis (ALS) and frontotemporal lobar degeneration (FTLD)." (PMID 37686239, 2023). "Mutations in a number of different genes, including C9ORF72, TDP43, FUS and SOD1, can all lead to some form of motor neuron disorder or the related cognitive disorder frontotemporal dementia." (PMID 37671010, 2023). "A repeat expansion in the C9orf72 (C9) gene is the most common genetic cause of amyotrophic lateral sclerosis (ALS) and frontotemporal dementia (FTD)." (PMID 37714849, 2023).
frontotemporal dementia (continued). "A GGGGCC hexanucleotide repeat expansion (HRE) in the first intron of the chromosome 9 open reading frame 72 (C9orf72) gene was discovered to be the most frequent cause of both frontotemporal dementia (FTD) and amyotrophic lateral sclerosis (ALS), as well as mixed FTD/ALS phenotype." (PMID 37511014, 2023). "Hexanucleotide repeat expansion in the gene C9ORF72 is a leading cause of amyotrophic lateral sclerosis (ALS) and frontotemporal lobar degeneration (FTLD)." (PMID 37250330, 2023). "The focus of this review will be on the analysis of published data related to three representative repeat expansion diseases: Huntington’s disease, C9orf72-frontotemporal dementia/amyotrophic lateral sclerosis, and myotonic dystrophy type 1." (PMID 37627588, 2023). "The C9orf72 hexanucleotide repeat expansion (HRE) is the most common genetic cause of amyotrophic lateral sclerosis (ALS) and frontotemporal dementia (FTD) in populations of European descent and especially common in Finland." (PMID 36936421, 2023). "The most common genetic cause of frontotemporal dementia (FTD) and amyotrophic lateral sclerosis (ALS) are hexanucleotide repeats in chromosome 9 open reading frame 72 (C9orf72)." (PMID 35993441, 2023). "The C9ORF72-linked diseases amyotrophic lateral sclerosis (ALS) and frontotemporal dementia (FTD) are characterized by the nuclear depletion and cytoplasmic accumulation of TAR DNA-binding protein 43 (TDP-43)." (PMID 37466726, 2023). "In the C9orf72 subtype of amyotrophic lateral sclerosis-frontotemporal lobar degeneration (ALS-FTD), the hexanucleotide (G4C2)RNA expansion (HRE) disrupts the nucleocytoplasmic transport of TFEB, compromising autophagy." (PMID 35507432, 2023). "Approximately 10–15% of ALS patients are also diagnosed with frontotemporal dementia (FTD), and particularly, these patients carry chromosome 9 open reading frame 72 gene (C9orf72) mutations." (PMID 37171577, 2023). "Intronic repeat expansions in the C9orf72 gene are the most frequent known single genetic causes of amyotrophic lateral sclerosis (ALS) and frontotemporal dementia (FTD)." (PMID 37138766, 2023). "Notably, this HRE in C9orf72 is also one of the primary genetic cause of frontotemporal dementia (FTD), the second most common form of early-onset dementia in individuals under 65 years, after Alzheimer’s disease (AD)." (PMID 37723585, 2023). "Expansions of a hexanucleotide repeat (GGGGCC) in the C9orf72 gene are the most common cause of familial ALS and frontotemporal dementia (FTD) (C9-ALS/FTD)." (PMID 37941028, 2023). "The hexanucleotide repeat, r(G4C2)exp, harbored in intron 1 of chromosome 9 open reading frame 72 (C9orf72) mRNA, causes genetically defined amyotrophic lateral sclerosis (ALS) and frontotemporal dementia (FTD) (c9ALS/FTD)." (PMID 37216594, 2023). "G4C2 hexanucleotide repeat expansions in a non-coding region of the C9orf72 gene are the most common cause of familial amyotrophic lateral sclerosis (ALS) and frontotemporal dementia (FTD)." (PMID 37644512, 2023). "C9orf72-associated ALS (C9orf72-ALS) is characterized by a wide range of phenotypic presentations, including a pure frontotemporal dementia (FTD) phenotype." (PMID 36980274, 2023). "C9orf72 gene repeat expansion is the most frequent genetic cause of ALS and of the related condition, frontotemporal dementia." (PMID 36589292, 2022). "Accordingly, carriers of autosomal dominant mutations in the genes associated with TAR DNA-binding protein 43 aggregation, such as Chromosome 9 open reading frame 72 (C9orf72) or progranulin (GRN), are at risk of later developing frontotemporal dementia." (PMID 36632182, 2022). "Chromosome 9 open reading frame 72 (C9orf72) is also fundamental to ALS because mutations in C9orf72 are the most frequent genetic cause of both ALS and related condition frontotemporal dementia, in European and North American populations." (PMID 35572138, 2022).
frontotemporal dementia (continued). "A ‘GGGGCC’ repeat expansion in the first intron of the C9orf72 gene is the most common genetic cause of amyotrophic lateral sclerosis (ALS) and frontotemporal dementia (FTD)." (PMID 35895140, 2022). "SOD1, TDP-43, frontotemporal dementia, and C9orf72 appeared to be pivotal in the molecular mechanisms of ALS." (PMID 36033620, 2022). "The loss of von Economo neurons (VENs) and GABA receptor subunit theta (GABRQ) containing neurons is linked to early changes in social–emotional cognition and is seen in frontotemporal dementia (FTD) due to C9orf72 repeat expansion." (PMID 35152451, 2022). "Frontotemporal dementia (FTD) is the second cause of dementia with an age of onset < 65, and its most common mutations are in GRN, C9orf72, and MAPT genes." (PMID 35145377, 2022). "The predominant genetic abnormality in both frontotemporal dementia and amyotrophic lateral sclerosis is an expanded hexanucleotide repeat sequence in the C9orf72 gene." (PMID 35202463, 2022). "We studied the relatively common monogenic form of ALS and frontotemporal dementia (FTD) due to a hexanucleotide (G4C2) repeat expansion within the first intron of the C9ORF72 gene." (PMID 36121477, 2022). "Hexanucleotide-repeat GGGGCC expansions in the first intron of the C9ORF72 gene are the most commonly identified genetic cause of amyotrophic lateral sclerosis (ALS) and frontotemporal dementia (FTD)." (PMID 35646086, 2022). "Genetic mutations in TARDBP, C9orf72, MAPT and SOD1 have been used to classify frontotemporal dementia and amyotrophic lateral sclerosis." (PMID 35202463, 2022). "It has also been shown to bind the hexanucleotide repeat expansion (HRE) of the C9orf72 gene that is linked to the neurodegenerative diseases, amyotrophic lateral sclerosis (ALS), and frontotemporal dementia (FTD)." (PMID 35791380, 2022). "Genetic variants in transmembrane protein 106 B (TMEM106B) are genetic modifiers of frontotemporal lobar degeneration with TDP-43 pathology (FTLD-TDP) in patients with pathological G4C2 hexanucleotide expansions in C9orf72." (PMID 36619668, 2022). "Clinical and genetic overlap exists with frontotemporal dementia (FTD), which is caused by mutations in C9orf72, MAPT, GRN, TARDPB, VCP, as well as other genes." (PMID 35493319, 2022). "A hexanucleotide G4C2 repeat expansion in the first intron of the C9orf72 gene is the most common cause of familial amyotrophic lateral sclerosis (ALS) and frontotemporal dementia (FTD) spectrum disorder." (PMID 34297726, 2021). "When the non-coding repeat expansion in the C9ORF72 gene was discovered to be the most frequent cause of frontotemporal dementia (FTD) and amyotrophic lateral sclerosis (ALS) in 2011, this gene and its derived protein, C9ORF72, were completely unknown." (PMID 34025358, 2021). "G4C2 Hexanucleotide repeat expansions in C9orf72 are strongly associated with amyotrophic lateral sclerosis (ALS) and frontotemporal dementia (FTD), mostly in European and North American populations." (PMID 34440384, 2021). "Expansions in the gene C9orf72 were related to a significant increase of the bulbar phenotype, and patients with bulbar phenotype had an increased risk of developing cognitive impairment and were more likely to develop frontotemporal dementia (FTD)." (PMID 34630279, 2021). "The most common genetic cause of amyotrophic lateral sclerosis (ALS) and frontotemporal dementia (FTD) is the presence of poly-PR/GR dipeptide repeats, which are encoded by the chromosome 9 open reading frame 72 (C9orf72) gene." (PMID 34768862, 2021). "HRE in C9ORF72 is also one of the main genetic causes of frontotemporal dementia (FTD)." (PMID 33619157, 2021). "G4C2 hexanucleotide repeat expansion in the noncoding region of the chromosome 9 open reading frame 72 (C9orf72) gene has been considered as the most prevalent genetic cause of amyotrophic lateral sclerosis (ALS) and frontotemporal dementia (FTD) recently." (PMID 36697556, 2021).